SLCO1A2 (solute carrier organic anion transporter family member 1A2)
Description:
Na(+)-independent transporter that mediates the cellular uptake of a broad range of organic anions such as the endogenous bile salts cholate and deoxycholate, either in their unconjugated or conjugated forms (taurocholate and glycocholate), at the plasmam membrane. Responsible for intestinal absorption of bile acids (By similarity). Transports dehydroepiandrosterone 3-sulfate (DHEAS), a major circulating steroid secreted by the adrenal cortex, as well as estrone 3-sulfate and 17beta-estradiol 17-O-(beta-D-glucuronate). Mediates apical uptake of all-trans-retinol (atROL) across human retinal pigment epithelium, which is essential to maintaining the integrity of the visual cycle and thus vision. Involved in the uptake of clinically used drugs. Capable of thyroid hormone transport (both T3 or 3,3',5'-triiodo-L-thyronine, and T4 or L-tyroxine). Also transports prostaglandin E2. Plays roles in blood-brain and -cerebrospinal fluid barrier transport of organic anions and signal mediators, and in hormone uptake by neural cells (By similarity). May also play a role in the reuptake of neuropeptides such as substance P/TAC1 and vasoactive intestinal peptide/VIP released from retinal neurons. May play an important role in plasma and tissue distribution of the structurally diverse chemotherapeutic drugs methotrexate and paclitaxel. Shows a pH-sensitive substrate specificity which may be ascribed to the protonation state of the binding site and leads to a stimulation of substrate transport in an acidic microenvironment. Hydrogencarbonate/HCO3(-) acts as the probable counteranion that exchanges for organic anions. May contribute to regulate the transport of organic compounds in testis across the blood-testis-barrier (Probable).
Synonyms: OATP1A2; OATP; SLC21A3; OATP-A
Tractability: Antibody: UniProt places it where antibodies can reach, with high confidence; its Gene Ontology location is reachable by antibodies, with high confidence; UniProt predicts a signal peptide or a membrane-spanning region; the Human Protein Atlas places it where antibodies can reach.
Target class: Electrochemical transporter; SLC superfamily of solute carriers; SLC21/SLCO family of organic anion transporting polypeptides; Transporter
Gene: Protein-coding gene on chromosome 12 (21,264,600 to 21,419,676, reverse strand). Ensembl gene ENSG00000084453.
Subcellular location: Cell membrane; Basal cell membrane
Subcellular location (Human Protein Atlas): Plasma membrane
Pathways (Reactome):
Drug ADME: Ciprofloxacin ADME
Metabolism: Recycling of bile acids and salts
Transport of small molecules: Organic anion transport by SLCO transporters
Gene Ontology:
Molecular function: protein binding; transmembrane transporter activity; bile acid transmembrane transporter activity; secondary active transmembrane transporter activity
Biological process: bile acid and bile salt transport; sodium-independent organic anion transport; transmembrane transport; xenobiotic metabolic process
Cellular component: basal plasma membrane; plasma membrane; apical plasma membrane; basolateral plasma membrane; membrane
Genetic constraint (gnomAD): Loss-of-function variants: 26 observed, 29.12 expected, observed/expected ratio (o/e) 0.89, 90% interval 0.65 to 1.24. The upper end of that interval is the gene's LOEUF score, 1.24, which puts it in group 5 of 6, group 1 being the genes least tolerant of losing a copy. Missense variants: 412 observed, 433.58 expected, observed/expected ratio (o/e) 0.95, 90% interval 0.88 to 1.03. Synonymous variants: 136 observed, 148.4 expected, observed/expected ratio (o/e) 0.92, 90% interval 0.8 to 1.06.
Homologues: Orthologues: chimpanzee SLCO1A2 (99% identical), macaque SLCO1A2 (96% identical), dog SLCO1A2 (87% identical), pig SLCO1A2 (84% identical), rabbit SLCO1A2 (83% identical), mouse Slco1a4 (73% identical), mouse Slco1a5 (73% identical), rat Slco1a5 (72% identical), rat Slco1a5 (71% identical), mouse Slco1a1 (69% identical), rat Slco1a8 (68% identical), rat Slco1a1 (67% identical), and 6 more. Paralogues in human: SLCO1C1 (44% identical), SLCO1B1 (40% identical), SLCO1B3 (39% identical), SLCO3A1 (33% identical), SLCO2A1 (30% identical), SLCO2B1 (29% identical), SLCO5A1 (28% identical), SLCO4A1 (25% identical), SLCO4C1 (25% identical), SLCO6A1 (21% identical).
Diseases named in the same sentence as SLCO1A2 in open-access papers:
SLCO1A2 is named in the same sentence as 88 diseases in open-access papers, as found by Europe PMC text mining. Sharing a sentence is not in itself a finding about the gene and the disease. The quoted sentences say what the papers report.
breast carcinoma (20 papers, 2013 to 2025). "PXR affects the expression of SLCO1A2 in breast cancer cells." (PMID 36839686, 2023). "Activation of SLCO1A2 is related to the development and functioning of the immune system, organismal system for calibrated responses to potential internal or invasive threats and is highly over expressed in breast cancer tissues." (PMID 33287006, 2020). "SLC22A2, SLC22A16, and SLCO1A2 were not expressed in any of the investigated breast cancer cell lines (Ct values > 35)." (PMID 35008681, 2021). "Expression of ABCB1, ABCC2, ABCG2, SLC22A16, and SLCO1A2 was significantly higher in normal breast tissue compared to tumorous tissue, while SLC22A1 and the tumor marker ESR1 showed a significantly higher expression in breast cancer tissue." (PMID 35008681, 2021). "SLCO1A2 protein expression has been detected in the cell membrane and cytoplasm of breast carcinoma cells but not in cells of adjacent healthy tissues." (PMID 32388639, 2020). "Silencing of SLCO1A2 did not affect DOX mediated cell death in BT549 breast cancer cells at reported circulating or even at lower concentrations, suggesting that other key transporters may mediate DOX-related cell death in BT549 breast cancer cells." (PMID 34230586, 2021). "Moreover, OATP1A2/SLCO1A2 and OATP1B3/SLCO1B3 mRNA and protein expression was significantly higher in malignant breast cancer tissue as compared to the surrounding non-malignant tissue." (PMID 36839686, 2023).
prostate carcinoma (7 papers, 2011 to 2020). A carcinoma that arises from epithelial cells of the prostate gland. "In the prostate, SLCO1A2 may play a role in the growth of prostate cancer cells through DHEA-S uptake suggesting that inhibition of this SLCO1A2 could help to attenuate tumour cell growth." (PMID 32388639, 2020).
colon cancer (4 papers, 2011 to 2023). "Due to the unique role of this transporter in pharmacokinetics and its ability to transport chemotherapeutics, we assumed that SLCO1A2 might be an effective target for treating colon cancer." (PMID 38045683, 2023). "Collectively, we screened the six LMGs including CYP19A1, FABP4, LRP2, SLCO1A2, PPARGC1A and ALOXE3, and constructed a signature to predict prognosis and immunotherapeutic response in colon cancer, which was extendedly and externally validated." (PMID 37055842, 2023). "Secondly, we studied the expression and pathophysiological significance of CYP19A1 in vitro and in vivo, and further studies are needed on other LMGs including FABP4, LRP2, SLCO1A2, PPARGC1A and ALOXE3 in colon cancer." (PMID 37055842, 2023). "The results showed that the expression levels of ACSL6, CYP19A1, LRP2, OSBPL3 and SLCO1A2 were considerably increased, while those of ACOX1, FABP4, PLAAT5, PPARGC1A and TNFAIP8L3 were decreased in colon cancer." (PMID 38045683, 2023). "Here we integrated CYP19A1, FABP4, LRP2, SLCO1A2, PPARGC1A and ALOXE3 with clinicopathological information of patients to construct a prognostic nomogram in colon cancer." (PMID 37055842, 2023).
progressive supranuclear palsy (4 papers, 2012 to 2022). A rare late-onset neurodegenerative disease characterized by supranuclear gaze palsy, postural instability, progressive rigidity, and mild dementia. "In addition to AD, a SLCO1A2 genetic variant is associated with progressive supranuclear palsy." (PMID 35682902, 2022). "Variants in the solute carrier organic anion transporter family member 1A2 (SLCO1A2) have been reported to be associated with statin-induced myopathy and progressive supranuclear palsy, an uncommon brain disorder that affects, among others, movement, control of walking (gait) and balance." (PMID 34214102, 2021).
diabetes (3 papers, 2012 to 2022). "In diabetes mellitus, the association of CA variant in rs11568563 (SLCO1A2) of the recipient was confirmed, and OR was even lower (0.550; p-value = 0.002)." (PMID 35214086, 2022). "However, the results reported that the CA variant in gene SLCO1A2 rs11568563 of the recipient was statistically associated with a lower risk (OR: 0.705; p-value = 0.002) of suffering from diabetes mellitus." (PMID 35214086, 2022). "Other variants in different locations of SLCO1A2, ABCC2 and ABCB1 transporter genes were associated with a lower risk of suffering from type 2 diabetes mellitus, chronic and acute nephrotoxicities and arterial hypertension." (PMID 35214086, 2022). "On the contrary, gene variants in SLCO1A2, ABCB1 and ABCC2 transporter genes were associated with a lower risk of suffering from type 2 diabetes mellitus, arterial hypertension and acute and chronic nephrotoxicities." (PMID 35214086, 2022).
arterial hypertension (2 papers, 2022 to 2025). "Several genes (CCK, SLCO1A2, UGGT2) were identified as targets of drugs (diazoxide, nadolol, hydrochlorothiazide) used to treat hypertension, suggesting opportunities for drug repositioning and risk factor prevention." (PMID 40034430, 2025).
Cognitive impairment (2 papers, 2018 to 2023). Abnormal cognition is characterized by deficits in thinking, reasoning, or remembering. "In addition, a GV on chromosome 12 within the IAPP/SLCO1A2 genes (rs73069071) was shown to modify the association between cortical Aβ deposition on AD-related cognitive impairment and temporal lobe atrophy." (PMID 37085326, 2023). "Recently, a variation in SLCO1A2 (rs73069071) has been associated with cortical Aβ deposition in AD-related cognitive impairment and temporal lobe atrophy and they proposed that this variant may be a modifier of Aβ deposition on AD-related neurodegeneration." (PMID 29986742, 2018).
Hyperbilirubinemia (2 papers, 2013 to 2017). An increased amount of bilirubin in the blood. "Also we will focus on other candidate genes which can be associated with both hyperbilirubinemia and cholelithiasis in SCA such as SLCO1BI and SLCO1A2." (PMID 24167350, 2013).
triple-negative breast carcinoma (2 papers, 2020 to 2022). An invasive breast carcinoma which is negative for expression of estrogen receptor (ER), progesterone receptor (PR), and human epidermal growth factor receptor 2 (HER2). "In triple negative breast cancer, SLCO1A2 encodes organic anion-transporting polypeptide 1A2 (OA TP1A2), and the expression of OATP1A2 and organic cation transporter 6 was predicted to be an indicator of response to neoadjuvant chemotherapy." (PMID 36468004, 2022).
B-cell acute lymphoblastic leukemia (1 paper, 2023). A neoplasm of lymphoblasts committed to the B-cell lineage, typically composed of small to medium-sized blast cells. "In addition, miR-5189, miR-595, and miR-6083 that might affect SLC46A1, SLC19A1, and SLCO1A2 MTX transport gene regulation and could affect MTX levels in patients with B-cell acute lymphoblastic leukemia." (PMID 37971595, 2023).
benign bone tumors (1 paper, 2020). "In osteosarcoma, benign bone tumors, and bone metastases from primary tumors of different origin, SLCO1A2 mRNA expression levels were variable, making OATP1A2 a rather weak prognostic marker in these tumor entities." (PMID 32806706, 2020).
glomerulonephritis (1 paper, 2014). A renal disorder characterized by damage in the glomeruli. "The relative order of magnitude in transcript expression for glomerulonephritis patients was ABCC2>SLCO1A2>ABCB1 = ABCG2 for SLE and SLCO1A2>ABCC2>ABCB1>ABCG2 for SVV." (PMID 24548980, 2014). "Our studies demonstrated reasonable leukocyte expression of transporter transcripts (ABCC2, ABCB1, ABCG2; 90% of patients and SLCO1A2; 50% of patients) in the blood of glomerulonephritis patients." (PMID 24548980, 2014).
lung carcinoma (1 paper, 2023). "Involvement of highly significant DEGs including SLCO1A2, OLFM4, RTKN2, CYP1A1, and MUC5AC plays a key role in rheumatoid arthritis development.Highly significant DEGs including OLFM4, RTKN2, CYP1A1, MUC5AC, CYP2A6, PCK1, and PITX1 have been reported to encourage the development of lung cancer." (PMID 38137330, 2023).
mood disorder (1 paper, 2025). A cognitive disorder a disturbance in which the person's mood is hypothesized to be the main underlying feature. "SLCO1A2 (or OATP1A2) encodes a sodium-independent transporter that is crucial for transporting hormones across the blood-brain barrier into the central nervous system and has been suggested as a potential modulator of mood disorders." (PMID 40034430, 2025).
parasitemia (1 paper, 2017). "SLCO1A2 and SLCO1B1 genes were associated with the gametocytemia clearance rate over treatment time in GEE analyses adjusted for age, gender, co-medication, parasitemia baseline level, CYP2C8 genotypes and genetic ancestry." (PMID 28975866, 2017).
serous ovarian cancer (1 paper, 2017). "In contrast, the SLCO1A2, SLCO1B1, SLCO1B3, SLCO1C1, SLCO2B1, and SLCO4A1 genes were amplified in 4.7–7.4% of a total of 316 patients with serous ovarian cancer, with concurrent amplification of SLCO1A2/1B1/1B3/1C1 and SLCO1B1/1B3/1C1, and also SLCO1B3/1C1." (PMID 28674494, 2017).
tauopathy (1 paper, 2018). Neurodegenerative disorders involving deposition of abnormal tau protein isoforms (tau proteins) in neurons and glial cells in the brain. "Further studies are needed to understand the role of newly associated variants with PSP including the effect of SLCO1A2 variation in BBB function in PSP and the cis and trans regulatory effects of GWAS variants on gene networks associated with tauopathy." (PMID 29986742, 2018). "SLCO1A2 is the most important SLCO in the human brain, and the expression information collected from GTEx and Braineac confirms that it is highly expressed in the brain and in brain regions that are targets for tauopathy." (PMID 29986742, 2018).
cancer (37 papers, 2010 to 2025). A tumor composed of atypical neoplastic, often pleomorphic cells that invade other tissues. "OATP1A2 is encoded by SLCO1A2 gene, and its polymorphisms were mainly associated with cancer treatment pharmacokinetics." (PMID 28975866, 2017). "We next evaluated whether target cancer cells similarly utilize SLCO1A2 for transport of DOX." (PMID 34230586, 2021). "We identified two poorly characterized, human-specific transporters (SLCO1A2, SLCO1B3) whose loss of function protects against doxorubicin-cardiotoxicity, but does not affect cell death in cancer cells." (PMID 34230586, 2021).
tumor (28 papers, 2011 to 2026). "We found increased gene expression of SLCO1A2, 2B1, 1C1, and 4A1, with negligible 4A1 expression detected in non-tumor tissue." (PMID 36382105, 2022). "The expression level of the SLCO1A2 tumor group was higher than that of the normal group." (PMID 33937013, 2021). "In contrast, Pe1 EC markers, including SLCO1A2, ANXA3, and TSC22D1, were enriched in leading edge and infiltrating tumor regions." (PMID 34228647, 2021). "Interestingly, several BBB-related transporters, including SLC2A1, ABCG2, ABCB1, SLCO1A2, and ATP10A were significantly decreased in ECs in tumor core." (PMID 34228647, 2021). "For example, SLCO1A2 expression was decreased in colon/rectum tumours as well as stomach, ovary, lung and kidney compared with normal tissues." (PMID 32388639, 2020). "Indeed, there was a clear shift in the Ct values of SLCO1A2, 2B1, 1C1, and 4A1 in fresh-frozen tumor tissue when compared with non-tumor tissue." (PMID 36382105, 2022).
myopathy (9 papers, 2017 to 2025). A disease of the muscle in which the muscle fibers do not function properly. "Both rs4149056 in SLCO1B1 and rs4149000 in SLCO1A2 were significantly associated with both definite myopathy (P = 7.30 × 10−14 and P = 7.62 × 10−11, respectively) and the incipient or definite myopathy phenotype (P = 1.33 × 10−11 and 6.49 × 10−12)." (PMID 31220337, 2019). "Determination of whether the SLCO1A2 locus can act as an independent risk factor for statin myopathy will require a much larger sample size." (PMID 31220337, 2019). "The two SNPs that seem to be strongly associated with statin myopathy in the discovery and replication cohorts are within two gene loci (SLCO1B1 and SLCO1A2) that are in a strong block of linkage disequilibrium in the discovery cohort (data not shown)." (PMID 31220337, 2019).
SLCO1A2 also shares sentences with these, for which no sentence is quoted: cholestasis (5 papers); liver diseases (5); glioma (4); COVID-19 (3); ischemic stroke (3); Stroke (3); Alzheimer disease (2); chronic kidney disease (2); hepatocellular carcinoma (2); infection (2); rhabdomyolysis (2); Rotor syndrome (2); systemic lupus erythematosus (2); -immune diseases (1); adenoma (1); atherosclerosis (1); bladder cancer (1); brain disorder (1); brain tumours (1); breast adenocarcinoma (1); breast tumour (1); Cachexia (1); cavernous hemangioma (1); cholelithiasis (1); Cholestatic liver disease (1); Chronic myeloid leukemia (1); Cirrhosis (1); Cluster headache (1); colon adenocarcinoma (1); colon polyps (1).
A further 38 diseases each share a sentence with SLCO1A2 in 1 paper.